XIAP (X-linked inhibitor of apoptosis)
Diseases named in the same sentence as XIAP in open-access papers (continued):
Sharing a sentence is not in itself a finding about the gene and the disease.
retinoblastoma (4 papers, 2021 to 2024). A malignant tumor that originates in the nuclear layer of the retina. "Subsequent studies identified XIAP and ABCB1 as targets of miR-214-3p, and it was suggested that 214-3p sensitizes retinoblastoma cells to chemodrugs and promotes apoptosis by targeting XIAP (X-linked inhibitor of apoptosis) and ABCB1, which codes for the multi-drug resistance P-glycoprotein." (PMID 38256203, 2024).
rhabdomyosarcoma (4 papers, 2018 to 2020). A rare aggressive malignant mesenchymal neoplasm arising from skeletal muscle. "In combination with cisplatin, matrine can downregulate the expression of X-linked IAP (XIAP) and induce the apoptosis of rhabdomyosarcoma RD cells." (PMID 32477114, 2020).
Stroke (4 papers, 2015 to 2020). Sudden impairment of blood flow to a part of the brain due to occlusion or rupture of an artery to the brain. "For example, sex differences have been noted for post-stroke brain levels of miR-23a, a target of which is X-linked inhibitor of apoptosis (XIAP), such that miR-23 was decreased in males but increased in females." (PMID 31011481, 2019). "XIAP was proposed to be a vital regulator of sex difference in stroke, and miR‐23a can facilitate the differences by regulating XIAP." (PMID 32790238, 2020). "However, XIAP protein levels are decreased in both sexes after stroke, likely due to different levels of miR-23a, which binds to the XIAP 3′UTR, in male and female ischemic brain." (PMID 25821444, 2015). "At baseline, females have higher levels than males of brain mRNA for X-linked inhibitor of apoptosis (XIAP), the primary endogenous inhibitor of caspases, and stroke significantly decreases XIAP mRNA in females but not in males." (PMID 25821444, 2015). "Interestingly, inhibition of XIAP significantly increased infarct volume in females but not males, providing evidence for sex-specific effects of stroke on miRs." (PMID 31011481, 2019).
T-Cell Lymphoma (4 papers, 2020 to 2025). "For example, the BCL2 inhibitor venetoclax is approved for the treatment of several haematological malignancies, and the dual CIAP1/XIAP inhibitor tolinapant was granted orphan drug designation from the United States Food and Drugs Administration (FDA) for the treatment of T-cell lymphoma in 2020." (PMID 39886119, 2024).
atherosclerosis (3 papers, 2013 to 2022). A disease characterized by the build-up of fatty material and calcium deposition in the arterial wall resulting in partial or complete occlusion of the arterial lumen. "The molecular activity prediction analysis showed that TQ inhibition of IL-6 significantly attenuated the levels of Akt, NF-kB Complex, Ap1, ERK 1⁄2 STAT5 a/b, PTGS2, PI3K Complex, XIAP, and estrogen receptor in atherosclerosis." (PMID 35723378, 2022). "A previous study showed that overexpression of miR-122 in human aortic endothelial cells directly targeting and inhibiting XIAP produces pro-apoptotic effects that contribute to conditions that promote atherosclerosis development." (PMID 34702176, 2021). "It is reported that XIAP exists in endothelial cells and has anti-atherosclerosis effect." (PMID 34702176, 2021).
autoimmune disease (3 papers, 2014 to 2026). A disorder resulting from loss of function or tissue destruction of an organ or multiple organs, arising from humoral or cellular immune responses of the individual to their own tissue constituents. "Reviewing present literature for the contribution of some escapes genes including CD40L, IRAK-1, TLR7, CXORF21 and XIAP confirms their primary attributions to the female bias of autoimmune diseases especially SLE disease." (PMID 33297945, 2020). "Current literature also confirms contribution of some escapes genes including CD40L, IRAK-1, TLR7, CXORF21 and XIAP to the female bias of autoimmune diseases especially SLE disease." (PMID 33297945, 2020). "Phenotypes similar to those observed in XIAP deficiency, such as post‐transplant‐related HLH, autoimmune diseases, and intestinal graft‐versus‐host disease, may occur." (PMID 41556306, 2026). "Therefore, XIAP can assist in the pathogenesis of autoimmune diseases." (PMID 33297945, 2020).
cholangiocarcinoma (3 papers, 2011 to 2016). A carcinoma that arises from the intrahepatic biliary tree (intrahepatic cholangiocarcinoma) or from the junction, or adjacent to the junction, of the right and left hepatic ducts (hilar cholangiocarcinoma). "Because XIAP has a strong effect in cholangiocarcinoma cell lines to protect against cell death, we tested the effect of embelin on XIAP protein levels in human cholangiocarcinoma cell lines and found that embelin caused a reduction in XIAP in Mz-ChA-1 and KMCH cells." (PMID 24603802, 2014). "XIAP is a key discriminator for converting Type II to Type I death receptor signaling, thus, we considered loss of XIAP protein as a mechanism by which Hedgehog inhibition sensitized cholangiocarcinoma cells to TRAIL-induced apoptosis." (PMID 21483830, 2011). "Most importantly, we provide evidence that the miR-410/XIAP signaling pathway is deregulated in human cholangiocarcinoma tissues." (PMID 27259577, 2016). "Our findings suggest that the miR-410 is an important regulator of cholangiocarcinoma cell growth in vitro and in vivo, through regulation of the anti-apoptotic factor XIAP." (PMID 27259577, 2016). "Transfection of miR-410 in TFK-1 cholangiocarcinoma cells resulted in a significant reduction of XIAP mRNA levels in comparison to cells transfected with miR-NC." (PMID 27259577, 2016). "MiR-410 and XIAP mRNA levels were evaluated by real-time PCR analysis in 22 pairs of cholangiocarcinoma and adjacent normal tissues." (PMID 27259577, 2016). "We have identified miR-410 as an important suppressor of cholangiocarcinoma growth both in vitro and in vivo We demonstrated that miR-410 negatively modulates XIAP expression regulating this way the intrinsic apoptotic signaling pathway." (PMID 27259577, 2016). "Experimental analysis revealed that miR-410 regulates the colony formation ability and invasiveness of cholangiocarcinoma cells, through binding in the 3’UTR of the X-linked inhibitor of apoptosis protein (XIAP) anti-apoptotic factor." (PMID 27259577, 2016). "This latter explanation seems less likely based on our previous experiments showing that siRNA against XIAP caused increased apoptosis and increased caspase activity in KMCH cholangiocarcinoma cells." (PMID 24603802, 2014). "Recent mechanistic studies have revealed that increased cellular expression of the E3 ubiquitin-protein ligase X-linked inhibitor of apoptosis (XIAP) impairs TRAIL- and chemotherapy-induced cytotoxicity, promoting survival of cholangiocarcinoma cells." (PMID 24603802, 2014). "This study was undertaken to determine if pharmacologic antagonism of XIAP protein was sufficient to sensitize cholangiocarcinoma cells to cell death." (PMID 24603802, 2014). "In this study, we sought to assess the effects of embelin on XIAP protein levels, apoptosis, and proliferation in cholangiocarcinoma cells." (PMID 24603802, 2014). "To assess the potential for antagonism of XIAP in cholangiocarcinoma cells, we first determined XIAP expression at the protein level in several cell lines." (PMID 24603802, 2014). "Previous studies have found that siRNA-mediated depletion of XIAP was sufficient to sensitize cholangiocarcinoma cells to apoptosis." (PMID 24603802, 2014). "Treatment of cholangiocarcinoma cells with the small molecule triptolide resulted in decreased XIAP protein levels and increased sensitivity to TRAIL." (PMID 24603802, 2014). "XIAP is ubiquitously expressed at the mRNA level and has been shown to be induced in cholangiocarcinoma cells by the inflammatory mediator IL-6." (PMID 24603802, 2014). "Together, these data suggest that targeting XIAP in cholangiocarcinoma cells increases sensitivity to apoptosis." (PMID 24603802, 2014). "XIAP protects cholangiocarcinoma cells from apoptosis induced by chemotherapeutic drugs and by the death receptor ligand TNF-related apoptosis-inducing ligand (TRAIL)." (PMID 24603802, 2014).
cholangiocarcinoma (continued). "In conclusion, our study implicates Hedgehog stimulation of XIAP expression as a mechanism for TRAIL resistance in human cholangiocarcinoma cells." (PMID 21483830, 2011). "Furthermore, miR-410 and XIAP mRNA expression levels were inversely correlated in human cholangiocarcinoma tissues." (PMID 27259577, 2016). "Real-time PCR analysis evaluated miR-9 and XIAP mRNA levels in cholangiocarcinoma cells and tumors." (PMID 27259577, 2016). "Taken together, our study revealed a novel microRNA signaling pathway involved in cholangiocarcinoma and suggests that manipulation of the miR-410/XIAP pathway could have a therapeutic potential for cholangiocarcinoma." (PMID 27259577, 2016). "In addition, we identified an inverse relationship between miR-410 and XIAP mRNA levels in human cholangiocarcinomas." (PMID 27259577, 2016). "Next, we investigated whether the miR-410/XIAP signaling pathway is deregulated in human cholangiocarcinoma tissues." (PMID 27259577, 2016). "Based on the role of XIAP in preventing cholangiocarcinoma cell apoptosis, we hypothesized that embelin would increase cell death in combination with TRAIL." (PMID 24603802, 2014). "We employed malignant cholangiocarcinoma cell lines and used embelin to antagonize XIAP protein." (PMID 24603802, 2014). "Our investigation confirms that XIAP inhibition can switch to mitochondria-independent death receptor signaling and integrates this observation into the protective effects of constitutive Hedgehog signaling observed in cholangiocarcinoma cells." (PMID 21483830, 2011). "Finally, genetic inhibition of XIAP not only sensitized cholangiocarcinoma cells to TRAIL killing, but did so independently of mitochondrial involvement (i.e. in the presence or absence of Bid inhibition)." (PMID 21483830, 2011). "Given that increased levels of XIAP have been associated with chemo-resistance, and based on our data, it is possible that the miR-410/XIAP pathway may contribute to the refractoriness of human cholangiocarcinoma to conventional chemotherapy or radiation therapy." (PMID 27259577, 2016). "To further validate our findings of miR-410 regulation of XIAP expression, we have used a second (EGI-1) cholangiocarcinoma cell line." (PMID 27259577, 2016). "Herein, we demonstrate that inhibition of the oncogenic Hedgehog pathway represses the expression of XIAP and sensitizes cancer cells to TRAIL cytotoxicity, using cholangiocarcinoma cells as a model to study TRAIL resistance." (PMID 21483830, 2011). "Moreover, XIAP may not play a dominant role in apoptosis protection in these cholangiocarcinoma cell lines." (PMID 24603802, 2014).
chronic myeloid leukemia (3 papers, 2016 to 2020). "Silencing of EZH2 was reported to decrease XIAP expression in chronic myeloid leukemia cells." (PMID 30854231, 2019). "In summary, curcumin treatment might produce a P73-dependent apoptotic cell death in chronic myelogenous leukemia cells (K562), which was triggered by mitotic catastrophe, due to sustained BAX and survivin expression and impairment of the anti-apoptotic proteins BCL-2 and XIAP." (PMID 27832139, 2016).
clear cell renal carcinoma (3 papers, 2009 to 2014). A malignant epithelial neoplasm of the kidney characterized by the presence of lipid-containing clear cells within a vascular network. "In clear cell renal cancer, the XIAP expression is an independent prognostic marker as it correlates with tumor aggressiveness." (PMID 25120954, 2014). "During clear cell renal cancer progression, an increase of XIAP relative to SMAC/Diablo occurs, which may contribute to apoptosis resistance." (PMID 25120954, 2014).
colorectal tumor (3 papers, 2013 to 2022). "An enhanced expression of a number of IAPs, including cIAP1, IAP2, survivin, XIAP in colorectal tumors has been correlated with worse survival, disease recurrence, and liver metastasis, which defines poorer prognosis." (PMID 32486357, 2020). "We showed that silencing XIAP followed by TRAIL treatment of TRAIL-resistant RKO colorectal tumor cells mimicked the effect of 17-AAG or PI-103 plus TRAIL." (PMID 23852390, 2013).
diabetes (3 papers, 2022 to 2025). "X-linked inhibitor of apoptosis protein (XIAP) prevents apoptosis of islet β-cells and is considered as a therapeutic target against β-cell destruction in diabetes." (PMID 36344967, 2022).
enteropathy (3 papers, 2020 to 2025). "XIAP deficiency is typically characterized by CD-like enteropathy and perianal disease." (PMID 40474095, 2025).
esophageal squamous cell carcinoma (3 papers, 2019 to 2020). Esophageal squamous cell carcinoma (ESCC) is a type of esophageal carcinoma (EC) that can affect any part of the esophagus, but is usually located in the upper or middle third. "By targeting XIAP, which is upregulated in esophageal squamous cell carcinoma tissues, miR-381 induces caspase-3-dependent apoptosis in these cells." (PMID 33324542, 2020). "The expression of XIAP in esophageal squamous cell cancer (ESCC) tissues was determined by immunohistochemistry assay." (PMID 31548877, 2019). "Other studies previously reported a survival benefit for patients with lower expression of XIAP in comparison with patients expressing high levels of XIAP in esophageal squamous cell carcinoma (ESCC) but were not able to reveal a difference in OS in esophageal adenocarcinoma." (PMID 31151416, 2019).
ischemic stroke (3 papers, 2020 to 2024). A stroke disorder caused by obstruction of blood flow to the brain, due to thrombotic (local blood clot formation) or embolic (due to a blood clot or other material traveling from another site) event. "We aim to investigate the role of miR‐130a in the neurological deficit and angiogenesis in rats with ischaemic stroke by regulating X‐linked inhibitor of apoptosis protein (XIAP)." (PMID 32790238, 2020). "Smac/DIABLO released from the mitochondria can neutralize the protective effects of XIAP and subsequently promote caspase-3-mediated apoptosis after ischemic stroke." (PMID 38645497, 2024). "The results indicated that compared with the healthy control group, XIAP was significantly downregulated in the blood samples of patients with ischemic stroke." (PMID 35959150, 2022). "Taken together, these findings suggest that XIAP is directly targeted by miR-186-5p, and it is downregulated in the blood samples of patients with ischemic stroke." (PMID 35959150, 2022). "Nevertheless, the function of miR‐130a targeting XIAP in ischaemic stroke has scarcely been investigated." (PMID 32790238, 2020). "Then, we determined the level of XIAP in the blood samples of patients with ischemic stroke." (PMID 35959150, 2022). "Thus, our study is intended for the exploration of miR‐130a's role in MCAO rats and OGD‐treated neurons to clarify its effect on ischaemic stroke by regulating XIAP." (PMID 32790238, 2020). "Nevertheless, the role of miR‐130a targeting XIAP in ischaemic stroke remains largely unknown." (PMID 32790238, 2020). "Our findings provide new clues for the role of miR‐130a/XIAP axis in MCAO rats and create new inspirations for the treatment of ischaemic stroke, which is of great realistic significance." (PMID 32790238, 2020).
macrophage activation syndrome (3 papers, 2021 to 2023). A complication of rheumatic disease that is caused by excessive activation and uncontrolled proliferation of T lymphocytes and well-differentiated macrophages. "Patients presenting with macrophage activation syndrome (MAS) should also be considered for XIAP deficiency testing." (PMID 34222142, 2021).
metastatic melanoma (3 papers, 2007 to 2025). A melanoma that has spread from its primary site to another anatomic site. "We are currently collecting specimens from a randomized clinical trial in which metastatic melanoma patients on the control arm are being treated with chemotherapy alone, and we will assess XIAP levels and the association with chemotherapy response." (PMID 17257402, 2007). "In total, we analysed the expression of six pro-apoptotic (Bax, Bak, Smac, Procaspase-9, Apaf-1, Procaspase-3) and three antiapoptotic proteins (Bcl-2, Bcl-xL, XIAP) in metastatic melanoma samples spotted on TMAs." (PMID 32054850, 2020). "In this study, we therefore assessed the expression of nine apoptosis regulators (Bax, Bak, Bcl-2, Bcl-xL, Smac, Procaspase-9, Apaf-1, Procaspase-3 and XIAP) in metastatic melanoma tissues by immunohistochemistry (IHC), using antibodies that passed rigorous validation." (PMID 32054850, 2020). "Targeting XIAP warrants additional investigation as a therapeutic approach for metastatic melanoma." (PMID 17257402, 2007).
myocardial ischemia (3 papers, 2002 to 2025). A disorder of cardiac function caused by insufficient blood flow to the muscle tissue of the heart. "Alterations of pro-survival proteins such as the inhibitor of apoptosis protein on chromosome X (xIAP) and the apoptotic repressor protein (ARC) have not been evaluated in a murine model of cardiac ischemia." (PMID 12805954, 2002).
ovarian clear cell cancer (3 papers, 2015 to 2020). An invasive malignant neoplasm that arises from the ovary and is characterized by a predominance of clear and hobnail malignant epithelial cells. "In a cohort of 90 ovarian clear cell carcinoma patients high XIAP expression was found to correlate with lower chemotherapy response rates and also a worse progression free and overall survival for patients." (PMID 26071313, 2015).
preeclampsia (3 papers, 2012 to 2025). Preeclampsia is a hypertensive disorder of pregnancy that is characterized by new-onset hypertension with proteinuria presenting after 20 weeks of gestation, and depending on mild or severe forms may initially present with severe headache, visual disturbances, and hyperreflexia. "In preeclampsia, overexpression of miR-515-5p suppresses XIAP (X-linked inhibitor of apoptosis protein) expression, promotes apoptosis, and reduces trophoblast migration, suggesting its involvement in placental dysfunction and disease development." (PMID 40369565, 2025). "The X-linked inhibitor of apoptosis protein (XIAP) is an inhibitory protein of apoptosis (IAP); the expression of XIAP in trophoblasts is decreased in preeclampsia, which may be associated with increased apoptosis in the placenta." (PMID 38338700, 2024). "By contrast, XIAP (the X-linked inhibitor of apoptosis protein) and survivin, two critical inhibitors of apoptosis, were not altered in preeclampsia." (PMID 22929622, 2012).
renal fibrosis (3 papers, 2020 to 2022). A final common manifestation of a wide variety of chronic kidney diseases characterized by glomerulosclerosis and tubulointerstitial fibrosis. "In addition, apocynin was found to down-regulate the NLRP3/X-linked inhibitor of apoptosis protein (XIAP) signaling and alleviate renal fibrosis in diabetic rats." (PMID 34631209, 2021). "XIAP functions as a caspase inhibitor, the expression of which is also decreased by the grape seeds with antioxidant activity, suggesting that XIAP may be involved in the NLRP3 inflammasome activation and renal fibrosis by regulating ROS." (PMID 33390969, 2020).
rheumatoid arthritis (3 papers, 2012 to 2020). A chronic, systemic autoimmune disorder characterized by inflammation in the synovial membranes and articular surfaces. "KE-298, an anti-rheumatic drug, specially augments apoptosis of activated T cells in rheumatoid arthritis by decreasing the expression of X-linked inhibitor-of-apoptosis protein." (PMID 23029367, 2012). "In patients with rheumatoid arthritis, curcumin is able to up regulate pro-apoptotic Bax, and down regulate anti-apoptotic B-cell lymphoma 2 (Bcl-2) and X-linked inhibitor of apoptosis protein (XIAP), inducing apoptosis and, therefore, inhibit the growth of synovial fibroblasts." (PMID 26927041, 2016).